IDO1 (indoleamine 2,3-dioxygenase 1)
Diseases named in the same sentence as IDO1 in open-access papers (continued):
Sharing a sentence is not in itself a finding about the gene and the disease.
tumor (continued). "Among the genes upregulated in the tumor compartment (79 PanCK+ segments from 10 patients) of non-responders, the most differentially expressed were IDO1, HLA-F, S100A8, and S100A9." (PMID 37835599, 2023). "Indoleamine-2, 3-dioxygenase (IDO1) and Tryptophan-2, 3-dioxygenase (TDO) catalyze the conversion of L-tryptophan to N-formyl-kynurenine and thus play primary roles in metabolism, inflammation, and tumor immune surveillance." (PMID 37116709, 2023). "The induction of indoleamine-pyrrole 2,3 dioxygenase (IDO-1) on both myeloid and tumor cells results in decreased levels of tryptophan and the presence of immunosuppressive catabolites such as kynurenine (Kyn) that promote Treg activity and diminish T cell effector function." (PMID 38132455, 2023). "To verify that the RIME‐MLL1‐H3K4me3 axis is clinically associated with ESCC development, we performed immunohistochemistry analysis and evaluated CD68, MLL1, PD‐L1, IDO‐1, CD8 and GranB expression in tumour tissues from a cohort of ESCC patients (SYSUCC, n = 70)." (PMID 37712124, 2023). "An injectable and biocompatible hydrogel loaded with both Indoleamine 2, 3-dioxygenase 1 (IDO1) inhibitor and herpes simplex virus type 1 (HSV-1) displays synergistic anti-cancer effects in vivo by remodeling the tumor microenvironment and generating immune memory effects." (PMID 37296221, 2023). "Studies have shown that most tumor cells are positive for IDO1, and the strong expression of IDO1 in tumor tissue has also been identified as an independent negative prognostic factor for many cancers." (PMID 37334368, 2023). "Both kynurenine and IDO1 are confirmed as important regulators for body immune homeostasis.And AHR, an important sensor for bacterial indoles and kynurenine, also plays pivotal roles bacterial mediated tumor immune microenvironment." (PMID 36927689, 2023). "IDO1 as the key enzyme in tryptophan metabolism plays a vital role in differentiating CD4+ T cells into regulatory T cells in tumors, thereby promoting the immunosuppressive state of the tumor microenvironment." (PMID 37040510, 2023). "In the process of APOBEC mutagenesis, the increased expression of important immune checkpoint molecules, including PDCD1, TIGIT, HAVCR2, LAG3 and IDO1, and the elevated CYT score, which serves as cytotoxic effects and anti-tumor response, were highly suggestive of better immunotherapy response." (PMID 37215984, 2023). "In accordance with our previous data, the immunoblotting assay verified that in a tumor transfectant cell the IDO1 protein is not just confined to cytosol but can also associate with EEs." (PMID 37122718, 2023). "They identified tumor-infiltrating CD4+ and CD8+ lymphocytes in their PDX humanized mouse model and further observed that T cell depletion led to reduced IDO1 expression, suggesting that T cells may increase IDO1 expression in human GBM." (PMID 37366911, 2023). "Moreover, tumor formation of CRISPR Ido1-KO mice (LLC-CRSG2) was significantly slower than control LLC-CR, and treatment with AT-0174 further suppressed LLC-CRSG2 tumor growth and weight." (PMID 37226257, 2023). "The expression of both IDO1 and COX-2 is increased in tumor cells and may interface with increased activity of TNF-related apoptosis-inducing ligand (TRAIL)." (PMID 37296860, 2023). "Spatial analysis of the tumor microenvironment from a non-responding S2 sample identified elevated protein expression of the immune suppressive checkpoint marker IDO1." (PMID 37105962, 2023). "RIME‐MLL1 increases H3K4me3 levels in the promoter regions of programmed death‐ligand 1 (PD‐L1) and indoleamine 2,3‐dioxygenase 1 (IDO‐1), constitutively increasing the expression of PD‐L1/IDO‐1 in tumour cells and inhibiting CD8+ T cells infiltration and activation." (PMID 37712124, 2023).
tumor (continued). "The enzyme indoleamine 2,3-dioxygenase 1 (IDO1) converts the essential amino acid tryptophan (Trp) to kynurenine (Kyn), thereby leading to an overall depletion of this critical amino acid within the TME and tumor draining lymph nodes." (PMID 37114134, 2023). "Indoleamine 2,3-dioxygenase 1 (IDO1) drives tumor immunosuppression in HGSOC by depleting local tryptophan and producing kynurenine inhibition, which is responsible for the downregulation of CD8+ tumor infiltrating lymphocytes (TILs)." (PMID 37033645, 2023). "Furthermore we assessed the presence of immune checkpoint biomarkers (IDO1, ICOS, LAG3 and PD-L1) on tumour epithelial and inflammatory cells across the sample tissues." (PMID 37527282, 2023). "IDO1 and TDO can be expressed constitutively by cancer cells, in which case they inhibit lymphocyte infiltration, or expressed by cancer and stromal cells in response to IFNγ, which limits the activity of tumour-infiltrating lymphocytes." (PMID 37936700, 2023). "Further, great potential is displayed by IDO1, SIGLEC-15, 4-1BBL, and HVEM in tumor proliferation regulation, which may become novel therapy targets in tumor treatment." (PMID 36358792, 2022). "In cancer, aberrant activation of IDO1 and TDO results in suppression of anti-tumor immunity." (PMID 35280684, 2022). "Results indicated that OXA could induce immunogenic death of tumor cells, while NLG919 inhibited activity of indoleamine 2,3-dioxygenase 1(IDO-1) in tumor cells, thereby overcoming the tumor immunosuppressive microenvironment." (PMID 35664731, 2022). "Rather, because immune cells with killing effects were activated by YH29407, which is an IDO1 inhibitor with high pharmacokinetics and pharmacodynamics, the inhibition of CD4+ T cells, which can differentiate into Tregs, may have helped in tumor suppression." (PMID 36545214, 2022). "W-0019482, the most potent IDO1 inhibitor identified from cell-based assays, reduced plasma and intratumoural ratios of kynurenine to tryptophan (K:T) and delayed the growth of subcutaneous GL261-hIDO1 tumours in mice." (PMID 36145311, 2022). "On the other hand, the transcript of the enzyme indoleamine 2,3-dioxygenase 1 (IDO1) is a direct target of miR-218-5p and, under conditions that dysregulate this miRNA, the expression of IDO1 increases, promoting immunological tolerance to tumor cells." (PMID 36362337, 2022). "It is tempting to speculate that while IDO1 affects the anti-tumor effect of NK cells in TME, it may also form an IDO1-NK cells/IFN-γ-IDO1 loop that can promote the increase of self-expression." (PMID 35681736, 2022). "We tested the expression of IDO1 in smoker and nonsmoker patients by western blot assay using lysates of tumor-normal paired lung tissues and found that IDO1 in normal lung tissues was higher than that in tumor samples of the nonsmoker patients." (PMID 36068203, 2022). "Additionally, in the tumor microenvironment, CD8+ T cells produce IFN-γ, stimulating upregulated expression ofPD-1/PD-L1 and IDO1 genes." (PMID 35800989, 2022). "IDO1 is the most studied and regulates immune cell function through the KYN pathway, and treatment combining immune checkpoint inhibitors (ICIs) with IDO1 blockade tends to inhibit tumour growth." (PMID 36217206, 2022). "In the tumor microenvironment, this immune escape mechanism is potentiated by the release of pro-inflammatory cytokines, such as IFN-γ, IL-1, IL-6, and TGF-β1, that in turn up-regulate IDO-1." (PMID 35328349, 2022). "Multiple cytokines in tumor microenhractures such as TNF-α, IFN-γ, IL-6, and IL-10 play a synergistic role by increasing the expression of IDO1, affecting catabolism of tryptophan, and promoting immunosuppressive response, which in turn promotes the initiation of cancer." (PMID 35444235, 2022). "This response promotes tumor catabolism and increases ubiquitin proteasomal degradation by accelerating phosphorylated cell signaling with transcriptional activator 3 (p-STAT3) and indoleamine 2,3-dioxygenase-1 (IDO1)." (PMID 35719333, 2022).
tumor (continued). "This phenomenon was attributed to the aNLG/Oxa(IV) lip inducing effective immunogenic death of tumor cells, although the immunosuppressive TME could be reversed by inactivating IDO-1." (PMID 35664731, 2022). "In the current study, IDO1 expression was increased in tumor tissue in KIRP, predicting worse OS, which suggested that IDO1 may serve as a potential target for KIRP." (PMID 36059952, 2022). "Inflamed tumors may also express IDO1 as an adaptive resistance mechanism, in which it is induced by IFN-γ produced by dendritic cells and tumor-infiltrated macrophages." (PMID 36145319, 2022). "While IDO1 and TDO can be found in the normal liver and lung, a recent study compared expression amongst 31 cancer types with normal tissue equivalents and found that expression was highest in the tumor tissue in all cases except liver and lung." (PMID 36230990, 2022). "In our clinical study, JAK1 inhibition combined with either IDO1 or PI3Kδ inhibition did not lead to enhanced immune activation as evidenced by a lack of CD8+ T-effector cell infiltration into the tumor microenvironment." (PMID 35288468, 2022). "In other samples, tumor cells expressing IDO1 were observed without any sign of inflammation or T-cell infiltration." (PMID 36188218, 2022). "For instance, tumors exhibiting abundant infiltration of macrophages showed that blocking inflammasome activation enhanced suppressive effects on T cells and decreased PD-L1 and indoleamine 2,3-dioxygenase 1(IDO) expression in macrophages which interact with CAR-T and tumor cells." (PMID 36376979, 2022). "Preclinical studies demonstrated that IFN-γ resulting IDO1/aryl hydrocarbon receptor (AhR) dependent p27 induction could prevent STAT1 signaling, thus suppressing the process of tumor cell death and activating tumor dormancy program." (PMID 36032151, 2022). "In concurrence with NanoString analysis of our own tumor samples, these included IFN-γ signaling genes STAT1, CXCL10, and IDO1; antigen presentation molecules HLA-DQA1 and HLA-DRB1; important T cell molecules GZMB and IL7R; and B cell–related molecules CD79A and CXCL13." (PMID 35132960, 2022). "Results from a phase I/II clinical trial, which combined IDO1 inhibitor epacadostat and Ipilimumab for the treatment of metastatic melanoma, showed an objective response and no tumor progression in some patients." (PMID 36304470, 2022). "Mice immunized against the P1A antigen completely rejected transplanted P815B tumor cells, while the second group of mice treated similarly with P815B cells expressing IDO1 did not." (PMID 36188218, 2022). "To eliminate this confounding factor and generate data specifically reflecting the metabolic impact of IDO1 inhibition in vivo, we used an immunocompromised mouse model in which epacadostat had no impact on tumor growth under normal conditions." (PMID 33831358, 2021). "We found that single gene expressions of IDO1, PI3 and TRIM22 could influence the chemotherapy sensitivity of OC patients in "Analysis based on chemotherapy sensitivity of tumor immune-related genes" section." (PMID 34736480, 2021). "The results showed that the expression level of programmed death 1 (PD-1), PD-L1, indoleamine 2,3-dioxygenase 1 (IDO), and lymphocyte-activating 3 (LAG3) in METCorC1 was higher than in METCorC2 (p < 0.05), suggesting the deep contribution of tumor immune evasion in METCorC1." (PMID 34539658, 2021). "Activation of IDO1 in the KYN pathway has been reported to suppress the T cell immune response by activating or differentiating regulatory T lymphocytes (Treg), which can inhibit the proliferation of other T cells and thus prevent anti-tumor responses." (PMID 34943977, 2021). "For this, M-MDSCs and G-MDSCs isolated from NB-tumor-bearing mice were stimulated with DMSO or ibrutinib for 1 h, followed by the addition of IL6 and GMCSF for 24 h and analysis of mRNA expression of Arg, Ido1, and Tgfβ by qRTPCR." (PMID 33669187, 2021).
tumor (continued). "With increased tumor PD-L1, the expression of inhibitory checkpoint molecules (ICMs), including ADORA2A, BTLA, CD160, and PDCD1, was downregulated while the expression of IDO1 was upregulated." (PMID 33754038, 2021). "However, the correlation of IDO1 expression with HCC prognosis and its specific role in tumor development remain controversial." (PMID 34769098, 2021). "Intrinsically, parental ID8 tumor cells do not produce appreciable levels of IDO1 (data not shown), therefore, we generated a stable IDO1-expressing EOC cell line by retroviral transduction." (PMID 34025677, 2021). "Thus, the N-cadherin block is an optimal therapy because it disrupts PD-L1 and IDO-1 expression and abrogates the immunosuppressive effect elicited by IFN-γ pathways that are active in the tumor microenvironment." (PMID 33692219, 2021). "The IFN-stimulated IDO1/Kyn/AhR cascade is favoured over the JAK/STAT pathway in TRCs rather than in differentiated tumour cells." (PMID 34539663, 2021). "Protein expression comparisons of immune and tumor cells reveal that PD-L1 was predominantly expressed on tumor cells, while ICOS, IDO-1, LAG-3, and OX40 were predominantly present on immune cells, and TIM-3 and VISTA were expressed on both tumor and immune cells in similar proportions." (PMID 34093591, 2021). "There are several direct IDO1 inhibitors available, including epacadostat and navoximod that neither directly kill tumor cells, nor spontaneously initiate an immune response." (PMID 34422661, 2021). "Indoleamine 2,3-dioxygenase 1 (IDO1), a heme enzyme highly expressed upon stimulation with proinflammatory cytokines such as interferon-γ (IFN-γ), is activated to modulate the tumor microenvironment and potentially crucial in the development of certain cancer types." (PMID 34769098, 2021). "Strategies to concomitantly target the IDO1 and AHR pathways may overcome immune suppression and enhance anti-tumor immunity in EOC and other solid tumors." (PMID 34025677, 2021). "IDO1 and BTK are other small molecules involved in tumor progression." (PMID 34572263, 2021). "The connection between indoleamine 2,3-dioxygenase 1 (IDO1) and tumour dormancy – a quiescent state of tumour cells which has been consistently linked to metastasis and cancer recurrence – is rarely discussed despite the pivotal role of IDO1 in cancer development and progression." (PMID 34539663, 2021). "Apart from IDO1, overexpression of TDO2 in tumour cells has been shown to facilitate immune escape." (PMID 34680327, 2021). "Indoleamine-2, 3-dioxygenase-1 (IDO1) is an immune checkpoint and a key rate-limiting enzyme that breaks down tryptophan into kynurenine, which plays an important regulatory effect in tumor immunity." (PMID 33718227, 2021). "In the plot of B7-H3 versus IDO-1, molecular nonresponder ROIs tend to cluster in the top right, and coincide with high tumor proliferation." (PMID 34188042, 2021). "IDO1 can inhibit effector T cells and hyper-activating Tregs to induce immune suppression in T cells, while it is not expected to kill tumor cells directly." (PMID 34869309, 2021). "Meanwhile, Wnt5α was also reported to mediate IDO1 activity via a β-catenin dependent signaling pathway in dendritic cells, and facilitate the IDOs activation through the AhR-IL-6-STAT3 signaling loop in several tumor types." (PMID 34657603, 2021). "Future research should examine how the interplay between IDO1 and PGE2 may impact on the initiation and maintenance of tumour dormancy." (PMID 34539663, 2021). "As the transcription factor AhR together with IDO1 and TDO2 are present in tumor cells, it has been proposed that KYN could have a dual role in promoting cancer invasion and immune escape." (PMID 34943977, 2021). "At present, the roles of CXCL13, IDO1 and SPP1 in immune process of tumor have been studied." (PMID 34736480, 2021). "Indeed, tumor cells and infiltrating immune cells such as DCs and macrophages can up-regulate the kynurenine producing enzymes TDO and IDO1." (PMID 34075438, 2021).
tumor (continued). "Our data suggest that IDO-1 inhibition, or B7-H3 blockade, when used in combination with anti-PD1, may reduce tumor proliferation in GBM and perhaps improve therapy responses." (PMID 34188042, 2021). "In agreement with previous studies, the absence of IDO1 did not prevent tumor growth, but increased the efficacy of anti–CTLA-4 antibody that was maintained in the presence of Tα1." (PMID 32817121, 2020). "Still, tumor cell lines grown in vitro not necessarily represent the in vivo situation; we therefore analyzed the IDO1 abundance in clinical resection specimens." (PMID 32117235, 2020). "The lack of a good patient stratification strategy was additionally criticized, since patients included in this study had not been selected on the basis of IDO1 expression, although tumor IDO1 gene expression was assessed as part of the study." (PMID 33584686, 2020). "In addition, Astragaloside IV reduces the extracellular secretion of IDO1 by blocking the interaction of IDO1 and GBP1, thereby reducing T cell exhaustion and inhibiting tumor progression." (PMID 33552086, 2020). "However, immune checkpoint genes including IDO1, HAVCR2, PDCD1LG2, CD274, CTLA4, and TIGIT were significantly up-regulated in tumor samples (fold change >1.30, FDR q ≤ 1.0e-5)." (PMID 33257699, 2020). "As opposed to the gut, Tα1 did not induce IDO1 mRNA and, actually, decreased kynurenine production in the tumor mass while the tryptophan levels were slightly increased." (PMID 32817121, 2020). "In our series, neither metastases-free survival nor overall survival was significantly different between patients with level of CD8 TL tumor density below or above the median, or IDO1 positive or negative tumors." (PMID 32194552, 2020). "This analysis revealed specific IDO1+ tumor cells in Stat1flox/floxApcMin tumors that were absent in Stat1∆IECApcMin tumors." (PMID 32444775, 2020). "Indoleamine 2, 3-dioxygenase 1 (IDO1) is an enzyme that catalyzes the metabolism of tryptophan in the tumor microenvironment, high levels of which mediate the inhibition of cytotoxic T cells via macrophages, DCs, and tumor cells." (PMID 32195333, 2020). "STAT1 or IDO1 protein in tumor or stroma cells did not correlate with overall survival and metastasis-free survival of patients." (PMID 32444775, 2020). "Hereby, we show that the tumor endothelial cells up-regulate IDO1 upon CD40-stimulating immunotherapy in response to increased IFNγ-secretion by T-cells, revealing a novel immunosuppressive feedback mechanism whereby tumor vessels limit T-cell activation." (PMID 32231867, 2020). "Similar to primary microglia, we observed minimal Ido1 expression in hypothalami of tumor‐bearing and sham animals (data not shown)." (PMID 32039522, 2020). "Independent of its immunoregulatory effects, IDO1 has been shown to activate canonical Wnt-β-catenin signaling and promote tumor progression by decreasing the tryptophan/kynurenine ratio." (PMID 33065994, 2020). "Based on this assumption, it is not surprising that IDO1 is not induced by Tα1 at the tumor site, considering that B16 cells, although not expressing IDO1, are potent inducers of IDO1 in other cell types." (PMID 32817121, 2020). "Interestingly, EOC cells enriched from ascites showed constitutive phosphorylation of STAT1 and STAT3 and expression of IL-18BP and IDO1, suggestive of an in vivo role of STAT-activating cytokines in the EOC tumor environment." (PMID 32093058, 2020). "If a T-cell response toward IDO1 could be achieved and supported by agonistic CD40 therapy, this would have the dual benefit of targeting tumor endothelial cells and, in IDO1-expressing tumors, malignant cells." (PMID 32231867, 2020). "A third possibility raised is that TDO may compensate for inhibition of IDO1, and it has been suggested that dual IDO1/TDO inhibitors may result in more effective anti-tumor immunity." (PMID 33584686, 2020).